CAV1 (caveolin 1)
Diseases named in the same sentence as CAV1 in open-access papers (continued):
Sharing a sentence is not in itself a finding about the gene and the disease.
endothelial dysfunction (continued). "As mentioned, TSH can regulate endothelial function directly and therefore, the interaction between cav-1 and TSH may be another significant element to uncover the mechanism of endothelial dysfunction in SH state." (PMID 25452768, 2015). "Thus, our data suggested endothelial miR-3074-1-3p inhibition could rescue the hypoxia-induced endothelial dysfunction and subsequent defective OPC differentiation via Cav-1." (PMID 36357389, 2022). "The activation of eNOS-counterpart CAV-1 and lower HO-1 levels indicate endothelial dysfunction in the RL-treated group, which was absent after EDI treatment, suggesting that the EDI may efficiently inhibit oxidative cell damage." (PMID 34692789, 2021).
glaucoma (36 papers, 2011 to 2025). Increased pressure in the eyeball due to obstruction of the outflow of aqueous humor. "First, polymorphisms in Nos3 or Cav1 (a gene that encodes a scaffolding protein that sequesters eNOS) impart risk for ocular hypertension and glaucoma in multiple studies involving different populations." (PMID 39932792, 2025). "In this review, we discuss the known mechanisms of retinal cell injury in glaucoma with a particular focus on an important molecular mechanism underlying BDNF/TrkB signaling mediated by Cav-1 and Shp2 phosphatase and its implications in glaucoma pathogenesis." (PMID 37962455, 2024). "Several GWAS studies strongly linked a risk variant (rs4236601) on a region encoded Cav-1/2 genes as a risk factor in glaucoma pathogenesis." (PMID 37962455, 2024). "Genome-wide association studies (GWAS) have linked variations in Caveolin1/2 (CAV-1/2) gene loci as a risk factor in glaucoma." (PMID 37962455, 2024). "Later, several population-based studies provided evidence of CAV-1 association in glaucoma pathogenesis although the significance varies among the population groups." (PMID 37962455, 2024). "Mutations of Cav-1 gene are associated with an increased genetic risk of primary open-angle glaucoma development across various population cohorts." (PMID 36760400, 2023). "Limited studies have described Cav-1 involvement in circadian rhythms disruptions causing glaucoma development." (PMID 36760400, 2023). "The multiple roles of Cav-1 in modulating ocular health and glaucoma risk suggest the potential for new therapeutic strategies that increase Cav-1 expression or augment its downstream signaling." (PMID 36760400, 2023). "Cav-1 has been found to contribute significantly to ocular function, with mutations of Cav-1 being associated with a genetic risk of glaucoma development." (PMID 36760400, 2023). "As they are associated with glaucoma, caveolin-1 (CAV-1) and caveolin−2(CAV-2) are significant endocytosis-related proteins and their knockdown or mutation contributes to increased levels of ECM components and altered aqueous humor outflow rates." (PMID 35652098, 2022). "Mutations in the gene region of Cav1 and Cav2 have been identified as glaucoma-linked variants, and loss of Cav1 in mice leads to changes in retinal vessel morphology and electrophysiological decrease function of RGC." (PMID 35457104, 2022). "Polymorphisms at the caveolin-1/2 locus are associated with glaucoma and IOP risk and deletion of caveolin-1 (Cav1) in mice elevates IOP and reduces outflow facility." (PMID 32940661, 2020). "Here, we analyzed the role of Cav1 in an acute ocular hypertension model and confirmed the association of Cav1 with glaucoma in the animal model." (PMID 28878269, 2017). "Results from a genome-wide association study have suggested that the CAV1/CAV2 locus is associated with glaucoma, but this association and its potential underlying mechanisms need to be confirmed and further explored." (PMID 28878269, 2017). "In this study, we verified the association between Cav1 and glaucoma in an acute ocular hypertension animal model." (PMID 28878269, 2017). "Polymorphisms in the CAV1/2 genes that encode signature proteins of caveolae are associated with glaucoma, the second leading cause of blindness worldwide, and with its major risk factor, intraocular pressure (IOP)." (PMID 27841369, 2016). "A single-nucleotide polymorphism (SNP) rs4236601 at the CAV1/CAV2 locus is associated with primary open-angle glaucoma (POAG)." (PMID 27297022, 2016). "To analyze CAV-1 expression in the presence of an agent that causes glaucomatous insults by activating mechanisms relevant to glaucoma pathogenicity, we treated immortalized NTM and GTM cells with DEX." (PMID 22128235, 2011). "Interestingly, the activation of Shp2 is shown to be mediated through its interactions with the adapter protein Cav-1, the gene described as a risk factor for glaucoma." (PMID 37962455, 2024).
glaucoma (continued). "Polymorphisms in the CAV1/2 gene loci impart increased risk for primary open-angle glaucoma (POAG)." (PMID 35372369, 2022). "Mutations in Cav-1 have been identified as a major genetic risk factor for glaucoma." (PMID 34819834, 2021). "Interestingly, it has also been shown that TMCO1 functionally interacts with other glaucoma-associated genes including CAV1." (PMID 32545285, 2020). "Furthermore, genetic defects might also be associated with the pathogenesis of this disease and the discovery of the CAV-1 gene locus has been shown to confer an increased risk of glaucoma." (PMID 37962455, 2024). "However, the role of Cav1 in other important aspects of glaucoma, such as RGC loss, is still largely unknown." (PMID 28878269, 2017). "However, these expression data do provide some support to the hypothesis that variants in CAV1 or CAV2 may be the source of glaucoma risk mapped to chromosome 7q31." (PMID 21321670, 2011). "However, although the outflow pathway is dysfunctional, its morphology is largely preserved, and the anterior chamber iridocorneal angle is open, indicating that Cav1 KO mice may be a valuable model for studying the functional link between this risk gene and glaucoma pathophysiology." (PMID 41227293, 2025). "This study has confirmed the importance of Cav-1 and autophagy in the treatment of glaucoma with acteoside by altering Cav-1 expression and using autophagy inhibitors." (PMID 41030451, 2025). "We also more precisely evidenced that the negative association of Shp2 phosphatase and BDNF/TrkB signaling provides an in vivo protective effect under chronic experimental glaucoma conditions and it is effectively dependent on the Cav-1 protein." (PMID 37962455, 2024). "The review summarises these two molecules (Cav-1 and Shp2) as potential targets for neuroprotective therapy in glaucoma and potentially other neurodegenerative disorders." (PMID 37962455, 2024). "Negative association of Shp2 on BDNF/TrkB signaling is effectively dependent on the Cav-1 protein and provides an in vivo protective effect under experimental glaucoma conditions." (PMID 37962455, 2024). "Expression of Cav-1 in the ganglion cell layer, specifically, is in agreement with previously reported GWAS regarding the potential role of this protein in glaucoma pathogenesis." (PMID 37962455, 2024). "Overall, the vast implications of Cav-1 on various ocular mechanisms leading to glaucoma suggest a potential for new therapeutics to enhance Cav-1 expression, which has seen success in other neurodegenerative diseases." (PMID 36760400, 2023). "Cav-1 plays an important role in regulating various pathways involved in the “vascular theory” of glaucoma." (PMID 36760400, 2023). "Cav-1 therapeutics have shown promising outcomes for other disease, raising hopes that a similar approach can be applied to glaucoma prevention." (PMID 36760400, 2023). "On the back of increasing evidence of Cav-1 involvement in glaucoma, our own study in Cav-1 knockout mice showed defective NVC at the ONH as assessed by laser speckle flowgraphy." (PMID 36760400, 2023). "Future research should focus on exploring the intricate interplay between Cav-1 and vascular dysregulation and exploiting the translative potential of Cav-1 therapy for alternative glaucoma treatment." (PMID 36760400, 2023). "Our present study lends support to the vascular theory of glaucoma pathogenesis by demonstrating defective vascular autoregulation accompanying RGC dysfunction and further identifies the loss of Cav-1 as a possible causative factor." (PMID 34819834, 2021). "Cav-1 shows a high immunoreactivity in the retinal GCL 44,45 and the gene locus was identified to be associated with glaucoma in genome-wide association studies (GWAS) 46-49." (PMID 33995651, 2021).
glaucoma (continued). "This gene codes for a component of a membrane complex involved in vesicular trafficking process, a function similar to that of the Caveolin genes (CAV1 and CAV2) which have previously been associated with primary open-angle glaucoma." (PMID 24518671, 2014). "Common sequence variants near CAV1 (caveolin 1) and CAV2, two of the genes only associated with focal adhesions, were recently reported to be associated with primary open-angle glaucoma." (PMID 22312193, 2012). "DEX increased CAV-1 expression in immortalized glaucoma TM cells by 2.8±0.1 (n=3) fold at 24 h and 2.5±0.1 (n=3) fold at 48 h, compared to 1.3±0.06 (n=3) fold at 24 and 48 h in immortalized normal TM cells." (PMID 22128235, 2011). "Sequence tags from 2 recently identified glaucoma-related genes, lysyl oxidase 1 (LOXL1; associated with exfoliation glaucoma), and caveolin 1 and caveolin 2 (associated with POAG) were expressed in at least two libraries." (PMID 21528004, 2011). "Given the recent association study results, CAV1 and CAV2 have been implicated in glaucoma pathogenesis." (PMID 21321670, 2011). "Phosphorylation of CAV-1 at tyrosine 14 in normal and glaucoma TM cell lines was evaluated using a specific monoclonal antibody (Ab)." (PMID 22128235, 2011). "To summarize, enhancing Cav-1 expression and activity may prove to be a valuable glaucoma therapeutic target, as it is a molecule highly involved in several glaucoma mechanisms." (PMID 39596463, 2024). "Phosphorylation of Cav-1 in Tyr14 and transcriptional regulation of its expression may also have a potential role in glaucoma pathogenesis and TM cells." (PMID 37962455, 2024). "Cav-1 dysregulation resulted in ECM pathological changes observed in glaucoma." (PMID 37962455, 2024). "Recent data indicated that this might be at least in part due to in vivo interactions of Cav-1 with Shp2 phosphatase in the inner retina and their role in regulating TrkB signaling and mediating the integrity of inner retinal function in glaucoma conditions." (PMID 37962455, 2024). "Further translational or clinical research may focus on whether the therapeutic potential of Cav-1 can be exploited for neuroprotective effects in the human eye, possibly averting RGC loss and glaucoma development." (PMID 36760400, 2023). "Here we modulated Shp2 expression using intravitreal AAV administration and studied its impact on the retina using a combination of functional, biochemical and anatomical changes in the WT and Cav-1-/- mice under normal physiological and experimental glaucoma conditions." (PMID 33995651, 2021). "Further research into the interactions between BRB and caveolin-1 may provide valuable insight into specific factors that influence neurovascular coupling in glaucoma." (PMID 34819834, 2021). "Moreover, results showed that genetic ablation of Cav-1 protein imparted protection against the inner retinal functional deficits in experimental glaucoma." (PMID 33995651, 2021). "GAS7 may interact with other genes implicated in glaucoma pathogenesis such as MYOC, OPTN, WDR36, CAV1, nitric oxide synthase 2 (NOS2), forkhead box C1 (FOXC1), apolipoprotein E (APOE), amyloid precursor protein (APP), and clusterin (CLU)." (PMID 32545285, 2020). "Our data highlights the neuroprotective effect of Cav1 on acute ocular hypertension and suggests that Cav1 may serve as a novel therapeutic target for the treatment of glaucoma." (PMID 28878269, 2017). "Like most candidates found associated with diseases in GWAS, the association, function and mechanism of CAV1/CAV2 in glaucoma have not yet been fully explored." (PMID 28878269, 2017). "Here, we studied the function of caveolin-1 (Cav1) in an acute ocular hypertension glaucoma model." (PMID 28878269, 2017). "Our result indicates that Cav1 is a novel therapeutic target in acute ocular hypertension injury and that cavtratin may be a potential drug for glaucoma clinical trials." (PMID 28878269, 2017).
glaucoma (continued). "Having said that, no glaucoma-causing mutations have been identified either in CAV1 or CAV2 to date." (PMID 22876122, 2012). "The mechanism by which defects in either CAV1 or CAV2 might cause glaucoma is unknown, but it has been hypothesized that such mutations might lead to glaucoma by altering nitric oxide or transforming growth factor-β (TGF-β) signal transduction." (PMID 21321670, 2011). "Although no glaucoma-causing mutations have been identified in either CAV1 or CAV2 to date, the results of the recent genome-wide association study suggests their existence." (PMID 21321670, 2011). "This review systematically explores the complex interactions between Cav-1 and autophagy in cardiovascular, respiratory, digestive, endocrine, nervous, urinary, breast and reproductive, blood systems, and other diseases (such as systemic sclerosis and glaucoma)." (PMID 41030451, 2025). "This study aimed to investigate the pathophysiological significance of Cav-1-Shp-2 interactions and their possible role in mediating RGC damage in animal models of glaucoma." (PMID 33995651, 2021). "The goal of this study was to investigate the expression and regulation of caveolin 1 (CAV-1) and caveolin 2 (CAV-2) in normal and glaucoma trabecular meshwork (TM) cells." (PMID 22128235, 2011). "Current treatment for glaucoma relies heavily on IOP-lowering drugs, however, there is an immense potential for new therapeutic strategies that increase Cav-1 expression or augment its downstream signaling in order to avert vascular dysfunction and glaucomatous change." (PMID 34819834, 2021). "Our results indicate that integrin/FAK pathway is disrupted in the retina in experimental glaucoma conditions in WT but not in Cav-1-/- mice." (PMID 33995651, 2021). "The chromosome 7q31 locus is tagged by the minor allele of rs4236601 and contains two genes, CAV1 and CAV2, although no glaucoma-associated mutations in these genes have been found to date." (PMID 21321670, 2011). "CAV-1 and CAV-2 are expressed in normal and glaucoma tissue and TM cell lines." (PMID 22128235, 2011). "Expression in human retina and tissues of the aqueous humor outflow pathway does not prove that either caveolin 1 or caveolin 2 has a role in glaucoma pathogenesis." (PMID 21321670, 2011). "Regarding genetic glaucoma models, we considered the main hallmarks and limitations of DBA/2J, glutamate/aspartate transporter/excitatory amino acid carrier 1, myocilin, connective tissue growth factor, optineurin, purinergic receptor 2Y, caveolin 1, and endothelin-1 mice." (PMID 41227293, 2025). "Absence of Cav-1, nevertheless, leads to excessive eNOS activity resulting in cytotoxicity, loss of vascular tone, glial-cell mediated apoptosis, and RGC while blocking NO production has been directly correlated with a significant decline in RGC degeneration in experimental glaucoma model in rats." (PMID 37962455, 2024).
Hypertension (36 papers, 2007 to 2026). The presence of chronic increased pressure in the systemic arterial system. "Cav-1 has been implicated in the development of hypertension, suggesting the potential of Sm-p40 in treating hypertension." (PMID 39481080, 2024). "Caveolin-1 has been implicated in the pathophysiology of hypertension, mainly through its influence on ECs and vascular smooth muscle cells." (PMID 38067108, 2023). "A number of human diseases are related to mutations or loss of CAV-1, such as lipodystrophy, arterial hypertension, and cancers." (PMID 32357558, 2020). "Viral infections are sometimes associated with hypertension, and this clinical trial may further reveal the link between CAV-1 and diseases, providing data support for clinical applications." (PMID 32357558, 2020). "The aim of this study was to determine whether Hhcy homocysteinylates endothelial nitric oxide synthase (eNOS) and alters caveolin-1 expression to decrease nitric oxide bioavailability, causing hypertension and renal dysfunction." (PMID 30778103, 2019). "Similarly, in the vascular smooth muscle and heart muscle cells, CaV1.2 is alternatively spliced by RBFOX2 generating a variant with exon 9 inclusion (Cav1.2SM) and exon 33 (Cav1.2CM) skipping during hypertension." (PMID 29510724, 2018). "Caveolae, particularly Cav-1, play a crucial role in the development of hypertension and the subsequent impairment of the BBB." (PMID 40305173, 2025). "Previous studies have shown that disruption of Cav1 expression results in dysregulated NO production, leading to hypertension and atherosclerosis." (PMID 39684412, 2024). "Wang and colleagues established a hypertension model to elucidate the specific involvement of caveolin-1 in the control of hypertensive vascular remodeling through its influence on the Notch pathway." (PMID 38067108, 2023). "To corroborate the electron microscopy measurements of transcellular, not other cytoplasmatic vesicles, we analyzed the effects of hypertension and exercise on caveolin-1 expression, the main component of caveolae-mediated transcytosis." (PMID 36909225, 2023). "In conclusion, caveolin-1 plays a significant role in the pathophysiology of hypertension, shedding light on potential therapeutic targets for managing this complex cardiovascular condition." (PMID 38067108, 2023). "In this study, we show that during Hhcy, homocysteinylation of eNOS and upregulation of caveolin-1 results in decreased eNOS and NO production and a concurrent decrease in H2S leads to impaired vasomotor response, hypertension and poor renal perfusion." (PMID 30778103, 2019). "This study demonstrates that Hhcy reduces hydrogen sulfide (H2S) generation in the kidney and homocysteinylation of eNOS and upregulation caveolin-1 expression together reduce eNOS activity resulting in hypertension." (PMID 30778103, 2019). "The upregulation of Cav1 expression in the retina under acute ocular hypertension suggests that Cav1 is involved in the modulation of hypertension." (PMID 28878269, 2017). "Additional support also comes from clinical evidence that CaV1 blockers for hypertension treatment, e.g., 1,4-dihydropyridines (DHPs) appear to reduce the risk of PD." (PMID 28059704, 2017). "Another study documented a downregulation of Cav-1 in the heart of dogs with experimental hypertension." (PMID 24454806, 2014). "Dihydropyridines (DHPs) are L-type calcium channel (Cav1) blockers prescribed to treat several diseases including hypertension." (PMID 18464914, 2008). "A distinguishing feature of Cav1 channels is their sensitivity to 1,4-dihydropyridines (DHPs), which bind to the α1 subunit and are commonly prescribed to reduce hypertension in humans." (PMID 18464914, 2008). "In humans, alterations in Cav1 abundance or function result in a variety of diseases, including hypertension, Timothy Syndrome, and congenital stationary night blindness." (PMID 18464914, 2008).